NOTCH3 (notch receptor 3)
Diseases named in the same sentence as NOTCH3 in open-access papers (continued):
Sharing a sentence is not in itself a finding about the gene and the disease.
tumor (continued). "Besides, we further investigated the connection of NOTCH3 and immune cell infiltration in tumors by the Tumor Immunoassay Resource (TIMER)." (PMID 38906903, 2024). "Furthermore, the expression level of NOTCH3 showed a significant correlation with the tumor purity of gastrointestinal tumors and the extent of immune infiltration by different immune cells." (PMID 38906903, 2024). "For instance, NOTCH3 signaling can lead to the recruitment of immunosuppressive cell populations or the secretion of cytokines that dampen the effectiveness of the immune response against the tumor." (PMID 39286249, 2024). "In 2018, a review concluded that Notch3 signaling may play an important role in oncogenesis, tumor maintenance, and resistance to chemotherapy." (PMID 38571962, 2024). "Furthermore, our experiments showed that depletion of NOTCH3 inhibited tumor cell proliferation, migration, and invasion, and suppressed BLCA growth and metastasis in vivo." (PMID 39557868, 2024). "The tumor suppressive ability of miR-206 may be explained by directly inhibiting the NOTCH3 signaling pathway and indirectly interacting with other signaling pathways involving CDH2 and MMP-918." (PMID 38906903, 2024). "Interestingly, Notch-1 can also induce Notch-3, reflecting its context-dependent role as both a tumor suppressor and tumor promoter." (PMID 39272905, 2024). "Finally, we examined the role of Notch3 expression in tumor immune infiltration and tumor cell proliferation." (PMID 37284062, 2023). "Thus, we generated subcutaneous tumors from both the metastatic and the primary tumor derived cells and looked at the effect of Notch3 knockdown in both cases." (PMID 37202533, 2023). "Moreover, another study has proposed that DLGAP5 is a direct target of Notch3 and acts as a tumor suppressor by modulating the cell cycle in the G2/M phase, thereby repressing tumorigenesis and cell proliferation." (PMID 37958803, 2023). "Human EGFR, Notch1, Notch2, and Notch3 mRNA were all expressed in tumours." (PMID 37441599, 2023). "The combination of metformin, which upregulated KLF10 expression via phosphorylating AMPK, and evodiamine, a non-toxic Notch-3 methylation stimulator, delayed tumor growth of PDAC with KLF10 deficiency in mice without prominent toxicity." (PMID 37308977, 2023). "Therefore, the identification of NOTCH3 signaling as a mediator of RANKL and bone resorption in the tumor microenvironment suggests the potential use of anti-NOTCH3 antibodies as a therapeutic approach to halting bone destruction in the cancer setting." (PMID 37174109, 2023). "We observed that mRNA levels of YAP1 and Notch3/4 were upregulated in 3D cultured tumor cells." (PMID 37369642, 2023). "In addition, Notch3 participates in the filtration and activity of immune cells within the tumor microenvironment (TME)." (PMID 36647017, 2023). "In GC, NOTCH3 contributes to immune tolerance and promotes tumor development." (PMID 37723519, 2023). "Furthermore, GSI treatment and silencing NOTCH3 significantly abrogated IGF2BP3-mediated tumor-initiating ability." (PMID 37853162, 2023). "We found that Notch3 expression is positively related to tumor proliferation." (PMID 37284062, 2023). "The expression levels of Notch3 were gradually increased as the tumor progressed." (PMID 36647017, 2023). "It has been shown that NOTCH3 is a direct target of tumour-suppressive miR-491-5p and miR-875-5p." (PMID 35136410, 2022). "Similarly, the results also showed that Akt1 predominantly regulated retinal angiogenesis, tumor angiogenesis, EC proliferation, EC sprouting, Notch3 activation, and the inhibition of YAP." (PMID 35931736, 2022). "Additionally, in the BH treatment group, the expression of FOXO3a increased in the tumor tissues, whereas Notch3, β-catenin, and Bcl-2 protein levels decreased." (PMID 35463301, 2022).
tumor (continued). "Moreover, tumor cell apoptosis was evaluated by HE staining, and the mitotic index (Ki-67) and Notch3 signal were detected through immunohistochemistry (IHC) and Western blotting." (PMID 35463301, 2022). "The experimental results show that Notch3 inhibition might be a potent strategy to treat patients with drug resistance and tumor recurrence of NSCLC." (PMID 35463301, 2022). "Furthermore, we investigated the relationship between this model and TME, and the results indicated that CPEB1, NOTCH3, NUAK1, and PDPK1 were strongly associated with the expression of tumor checkpoints and tumor immune infiltration." (PMID 36072578, 2022). "It would be interesting to determine whether Notch3, which represses the proliferation of adult NSCs, contributes to the tumor suppressor activity of RBP-Jk in cooperation with Notch1 and Notch2." (PMID 36358826, 2022). "NOTCH3 is activated by chronic hypoxia and it is widely expressed throughout tumor angiogenesis." (PMID 35073251, 2022). "Furthermore, DCN, ITGB1, NOTCH3 and SPARC genes were discovered to be strongly associated not only with tumor response to nCRT but also with disease-free survival; they were further used to form a four-gene expression-based risk score." (PMID 35682714, 2022). "Furthermore, there were two genes (FBXW7, RET) mutated exclusively in tumours and eight (BLM, GJB2, NOTCH2, NOTCH3, NTRK1, POLE, SOS1, TSC2) solely in metastases." (PMID 34572946, 2021). "However, Notch3 was also found to act as a dependent receptor in tumor ECs to negatively regulate tumor angiogenesis, circumventing CSL." (PMID 34195229, 2021). "In addition, IL-6 signaling also promotes a tumor hypoxia-resistant/invasive phenotype by triggering NOTCH3-expressing stem/progenitor cells." (PMID 34374886, 2021). "The authors showed that the Fos-related antigen 1 protein, a regulator involved in cell proliferation, differentiation, and transformation and EMT promotion, is negatively regulated by Notch3 in tumor cells, thus revealing the onco-suppressive role of the receptor." (PMID 35582386, 2021). "The Notch signaling can also promote tumor migration via Notch3 activation." (PMID 33920054, 2021). "In addition, the relationships between Notch3 and other tumor biological characteristics, including metastasis and angiogenesis are also discussed." (PMID 34195229, 2021). "Notch3 is also involved in the regulation of tumor angiogenesis." (PMID 34195229, 2021). "In addition, Notch3 signaling can be activated by interactions between tumor cells and cells in the tumor microenvironment, which contribute to tumor angiogenesis in several cancers." (PMID 34195229, 2021). "Furthermore, NOTCH3 mRNA expression was negatively correlated with miR-491-5p expression in TCGA cohort, suggesting a regulatory effect of this tumor suppressor miRNA on NOTCH3 in GC." (PMID 33452458, 2021). "Matrix metalloproteinases (MMPs) cascade with Notch3 signaling and promote tumor metastasis." (PMID 34195229, 2021). "In CRC, NOTCH3 has been identified to drive tumor progression." (PMID 34733326, 2021). "Consistently, Notch3-modulating approaches have been successfully combined with cisplatin and carboplatin, increasing the DNA-damaging response and improving the sensitivity of cell lines and tumor xenografts to this agent." (PMID 34680255, 2021). "In the stromal microenvironment, many chemokines and cytokines may activate PI3K/AKT and Notch pathways, leading to tumor initiation and development, so we speculate that IL-8 may maintain the stemness of tumor cells through the PI3K/AKT/Notch3 pathway." (PMID 34277625, 2021). "Highly expressed NOTCH3 indicated advanced tumor stages and a poor overall survival rate." (PMID 34733326, 2021). "Considering that, in this tumor, Notch3 overexpression correlated with OS and that Notch3 silencing could counteract cisplatin resistance, Notch3 inhibition with SAHA could be applied as a potential therapeutic strategy." (PMID 34680255, 2021).
tumor (continued). "Increased NOTCH3 was observed in CRC and associated with accelerated tumor growth." (PMID 34733326, 2021). "Thus far, reports on the tumor-suppressive role of NOTCH3 have mainly focused on the canonical CSL-dependent signaling." (PMID 33775697, 2021). "NOTCH3 signaling may play an essential role in tumor aggressiveness, maintenance, and chemotherapy resistance." (PMID 33748290, 2021). "The expression of ADAM10, Notch1, Notch2, Notch3, Notch4, Hey1, vimentin and N‐cadherin at the transcript level was significantly upregulated, whereas transcripts of E‐cadherin significantly decreased in tumour tissues versus in normal liver tissues of HCC." (PMID 33955149, 2021). "In addition, Notch3 signaling also contributes to tumor chemoresistance against several drugs, including doxorubicin, platinum, taxane, epidermal growth factor receptor (EGFR)–tyrosine kinase inhibitors (TKIs) and gemcitabine, through complex mechanisms." (PMID 34195229, 2021). "Another main feature of Notch3 signaling is to induce tumor resistance against several kinds of chemotherapeutic drugs, including doxorubicin, platinum, taxane, epidermal growth factor receptor (EGFR)–tyrosine kinase inhibitors (TKIs) and gemcitabine (See in Notch3 and Drug Resistance)." (PMID 34195229, 2021). "NOTCH3 functions as a tumor suppressor by controlling p21-mediated cellular senescence." (PMID 32564008, 2020). "Importantly, further investigation revealed the correlation of NOTCH3 with tumor-infiltrating immune cells, immune checkpoint gene expression, and well-established biomarkers of ICB therapy." (PMID 33479597, 2020). "Furthermore, chemoresistance is decreased upon NOTCH3 blockage and the volume of a tumor upon xenograft is decreased." (PMID 32796631, 2020). "Moreover, high Notch3 is correlated with lower expression of β-catenin but higher aldehyde dehydrogenase (ALDH) activity, supporting the theory that Notch3 regulates tumor stemness through inactivation of Wnt/ β-catenin." (PMID 32466488, 2020). "The upregulation of integrin genes by Notch3 activation may also play a role in survival of detached tumor cells in the peritoneal fluid, which must evade detachment-induced apoptosis (anoikis) and lymphatic clearance." (PMID 32525899, 2020). "JAG1 is expressed in the tumor microenvironment by peritoneal mesothelium and tumor-associated endothelium and loss of JAG1 in adjacent cells reduces tumor cell adhesion and growth, suggesting that microenvironmental activation of Notch3 is critical in tumor progression." (PMID 32525899, 2020). "In addition, the most highly expressed Notch3 ligand in OC cells and mesothelial cells in the peritoneum is Jagged 1 (Jag1), which has been shown to promote OC cell proliferation and adhesion, suggesting a role for the Jag1/Notch3 axis in tumor dissemination." (PMID 32512891, 2020). "Here we show that the inhibition of NOTCH2 signaling by gliotoxin is associated with the recovery of a potentially non-canonical tumor suppressing NOTCH3 activity in CLL cells." (PMID 32570839, 2020). "Notch3 and Jag1, components of the Notch signaling pathway, were increased in expression and confirmed by protein expression analysis in the primary tumor and tumor cells." (PMID 32652895, 2020). "Similarly, patients with high NOTCH3 expression had a higher Tumor Immune Dysfunction and Exclusion (TIDE) signature, implying the failure of ICB therapy in the NOTCH3 High group." (PMID 33479597, 2020). "Based on the preclinical data, our hypothesis was that PDAC patients with higher levels of Notch3 gene expression in tumor cells would have an enhanced potential for therapeutic benefit from the addition of tarextumab to standard therapy." (PMID 31347292, 2019). "To assay whether Notch3-mediated regulation of Mdh1, Idh1 and Aco1 protein expression really occurs in primary tumours, we examined protein abundance in Notch3-silenced and control rats after brivanib treatment." (PMID 30765875, 2019).
tumor (continued). "Recent studies recommend that NOTCH3 signaling may play a major role in oncogenesis, tumor maintenance, and resistance to chemotherapy." (PMID 31552087, 2019). "Finally, they provided in vivo evidence that the tumor microenvironment—through activated cancer-associated fibroblasts—stimulated Notch3 signaling, which, in turn, enhanced LSD1 expression to facilitate tumor growth." (PMID 31756917, 2019). "All these studies support the notion that Notch3 activation may reprogram tumor cells to assume a stem-like profile and contribute to platinum chemoresistance in OC, which is responsible for tumor recurrence." (PMID 30723507, 2019). "Therefore, Notch3 and PKCθ converge on the hyperactivation of the canonical NF-κB pathway that rules over the developmental aspects and the activity of Tregs in the tumor microenvironment." (PMID 30364244, 2018). "Compendiously, the crosstalk between hyperactive Notch3 and canonical NF-κB pathways upregulates Foxp3 expression, thus enhancing the suppressive function of Tregs against protective antitumor immune responses in tumor microenvironments." (PMID 30364244, 2018). "Interestingly, ectopic expression of WWP2 decreases tumor development in a mouse xenograft model and suppresses NOTCH3-mediated effects, including increase in cancer stem cell-like cell population and platinum-resistance." (PMID 29389895, 2018). "This suggests that the endothelial expression of Notch3 limits tumour angiogenesis." (PMID 28719575, 2017). "Interestingly, reduced Notch3 expression resulted in decreased proliferation of T24 and J82 cells in vitro and lower tumor progression in vivo." (PMID 28416766, 2017). "Taken together these data support the view that Notch3 behaves as a dependence receptor in endothelial cells and that Jagged-1 expression in tumour may act as a pro-angiogenic mechanism by limiting Notch3 induced apoptosis in endothelial tumour cells." (PMID 28719575, 2017). "We uncovered here an unexpected function of Notch3 expression in tumour vasculature." (PMID 28719575, 2017). "Here we showed that Notch3 behaves as a dependence receptor, regulating tumour angiogenesis." (PMID 28719575, 2017). "Therefore, Notch3 is critical to the regulation of ovarian CSCs and tumor resistance and CSCs are important targets for overcoming chemoresistance." (PMID 29069826, 2017). "Consequently, we show that the well-documented anti-tumour effect mediated by γ-secretase inhibition is at least in part dependent on the apoptosis triggered by Notch3 in endothelial cells." (PMID 28719575, 2017). "This miRNA attenuated tumor proliferation and migration through downregulation of NOTCH3." (PMID 27938406, 2016). "To test this hypothesis, we isolated HTR cells (that is, from fulvestrant-treated and resistant tumours) and silenced Notch3 expression (shN3)." (PMID 26858125, 2016). "We have observed that endothelial Jagged1 contributes to tumor dysplasia through two distinct effects: a pro-angiogenic effect, increasing tumor vascular density, maturation and perfusion; and an angiocrine effect likely through Notch3/Hey1 stimulation of tumor cell proliferation." (PMID 26213336, 2015). "The downregulation of Notch3 in the QGY7701 cells resulted in the poor survival of tumor cells." (PMID 25668819, 2015). "However, because Nanog expression is positively correlated with Notch3, it is likely Notch3 functions as a governor to balance tumor cell proliferation and the maintenance of the CSC population by regulating the β-catenin pathway." (PMID 25668819, 2015). "This positive correlation of Notch3 and Hes1 expression (R2 = 0.78, p < 0.001, n = 32) suggests that higher expression levels of Notch3 in the tumor may result in an upregulation of Hes1 gene expression." (PMID 25668819, 2015). "Therefore, we suggest that endothelial Jagged1 is able to regulate tumor cell metabolism by its angiocrine function through Notch3/Hey1." (PMID 26213336, 2015).
tumor (continued). "We observed that tumor-induced decrease in the expression of Notch receptors, Notch1, Notch2, Notch3 and Notch4, as well as ligands Dll1, Dll4 and Jagged1 in splenocytes of 4T1HA and RencaHA tumor-bearing mice could be reversed by treatment with bortezomib." (PMID 26431276, 2015). "However, given that Notch3 hyper-activation showed a similar effect in both tumor cell subtypes, we can argue that the proliferative effects of Notch3IC do not absolutely require expression of the PAX3-FOXO1 fusion oncoprotein." (PMID 24797362, 2014). "Notch3 has been shown to be essential for tumor growth and development of drug resistance." (PMID 25356737, 2014). "Furthermore, ectopic expression of WWP2 decreased tumor development in a mouse xenograft model and suppressed the Notch3-induced phenotypes including increase in cancer stem cell-like cell population and platinum resistance." (PMID 25356737, 2014). "By immunohistochemisty, positive Notch3 expression was observed in each group in the vascular smooth muscle of small vessels, while weaker staining was observed in the alveolar epithelial cells of non-tumor tissues." (PMID 23420695, 2013). "Furthermore, in HeLa cells, miR-206 was reported to promote apoptosis through inhibition of Notch3 expression, thus resulting in inhibition of tumor cell migration." (PMID 23823624, 2013). "Notch3 promotes tumor cell growth and proliferation via the Hes gene in a CSL-dependent fashion." (PMID 23426998, 2013). "Overexpression of NOTCH3 leads to increased platinum resistance, whereas γ-secretase treatment, which inhibits intracellular transmission of the notch signal, restores sensitivity to therapy and depletes cancer stem cells in the tumor." (PMID 23528888, 2013). "In survival analyses, nuclear Notch3 and HEY-1 expression were significantly associated with reduced overall and disease-free survival following tumour resection with curative intent, with nuclear HEY-1 maintaining independent prognostic significance for both outcomes on multivariate analysis." (PMID 23226563, 2012). "We hypothesize that in cancer Notch3 is important for tumor survival, whereas Notch1 mediates the response to hypoxia through the regulation of angiogenesis." (PMID 22074495, 2011). "Expression of Notch1 and Notch3 was elevated in Hes1tg tumors A, C and D, as well as Id1tg tumor C." (PMID 19688092, 2009). "In addition, Notch receptor 3 (NOTCH3) influences the survival of tumor cells in various cancers." (PMID 40796704, 2025). "In addition, another study demonstrated that NRF2 enhances the expression of the antioxidant enzyme GPX2, which plays a pivotal role in maintaining cancer stem cell populations through the upregulation of NOTCH3, a key driver of tumor progression.NRF2 also has other pro-tumorigenic functions." (PMID 41187427, 2025). "Additionally, Jagged1 from CAFs interacts with Notch3 in tumor cells to regulate tumor resistance." (PMID 41050674, 2025). "In addition, cytoplasmic Jagged1 expression correlates with Notch3 expression in tumor cells." (PMID 41294868, 2025). "Furthermore, the crosstalk between hyperactivated Notch3 and the classical NF-κB pathway upregulates Foxp3 expression, thereby enhancing the ability of Tregs to suppress protective anti-tumor immune responses within the tumor microenvironment (TME)." (PMID 41458964, 2025). "Furthermore, its interaction with Notch‐3 also regulates self‐renewal and survival in mammary gland stem/progenitor cells, supporting its role in maintaining the stemness of cancer cells and contributing to tumour heterogeneity." (PMID 40690563, 2025). "Finally, we confirmed the role of Notch3 in tumor immune infiltration and tumor proliferation." (PMID 37284062, 2023). "Moreover, a novel mutation was discovered in Notch3 itself in the UT-SCC-74B cell line derived from the metastatic site which was not present in the UT-SCC-74A line derived from the primary tumor." (PMID 37202533, 2023).